GSDMC (gasdermin C)
Diseases named in the same sentence as GSDMC in open-access papers (continued):
Sharing a sentence is not in itself a finding about the gene and the disease.
melanoma (continued). "GSDMC was initially found to be highly expressed in metastatic melanoma cells, and was called MLZE (melanoma-derived leucine zipper-containing extranuclear factor)." (PMID 34381721, 2021). "GSDMC is originally isolated from melanoma cells, so it is known as a melanoma‐derived leucine zipper extranuclear factor (MLZE), whose gene is located on human chromosome 8q24.21." (PMID 34459122, 2021). "Studies have found that the expression of GSDMC was elevated in colorectal cancer, lung adenocarcinoma, and melanoma, and its expression promotes metastasis in patients with melanoma." (PMID 34778452, 2021). "Therefore, we analyzed the impact of PLAU and GSDMC expression on the prognosis of melanoma patients treated with ICIs." (PMID 41584044, 2026). "GSDMC, also known as melanoma‐derived leucine zipper‐containing extranuclear factor (MLZE), is the least characterized GSDM, though emerging roles in tumors, intestinal homeostasis, and gastrointestinal microbe‐sensing skin metabolism highlight its versatility." (PMID 41574659, 2026). "GSDMC expression is tumor-specific and often expressed in melanoma, lung cancer, and CRC." (PMID 39062587, 2024). "Another effector, GSDMC, was found to be expressed in malignant melanoma and may participate in the invasive and metastatic features of the cancer cells." (PMID 37305457, 2023). "Human GSDMC is preferentially expressed in metastatic melanoma cells." (PMID 35795683, 2022). "For instance, GSDMC was initially recognized as an oncogene in metastatic mouse melanoma." (PMID 36936274, 2022). "Studies have pointed out that high expression of GSDMC promotes melanoma metastasis." (PMID 36199146, 2022). "The biological functions of GSDMC and PJVK remain unknown, but it is reported that the expression level of GSDMC is positively correlated with the metastatic ability of melanoma cells, indicating the possible relationship between GSDMC and tumorigenesis." (PMID 35198448, 2022). "GSDMC, also known as melanoma-derived leucine zipper-containing extranuclear factor, was originally isolated from mouse melanoma cells and obtained from the mouse melanoma cell B16-BL6 cDNA library." (PMID 34858408, 2021). "The GSDMC gene (gasdermin C) was initially identified as a gene that is preferentially expressed in metastatic melanoma cells and also in the epithelium of the skin and gastrointestinal tract, while GWAS in humans revealed associations of variants in GSDMC with monocyte counts." (PMID 33731010, 2021). "In addition, whether upregulated GSDMC expression upon acquisition of metastatic potential in melanoma cells is only an accompanying phenomenon is unclear." (PMID 34858408, 2021). "GSDMC was originally identified as melanoma-derived leucine zipper extranuclear factor (MLZE), whose cDNA was isolated from a melanoma cell line." (PMID 27835699, 2016). "Other members of the gasdermin family of proteins have also been detected in melanoma as shown for GSDMC that was not expressed in the normal epidermis, but its elevated level in melanoma cells correlated with their metastatic potential." (PMID 32340261, 2020). "To ascertain the universality of GSDMC-enhanced PARPi sensitivity in cancers, we stably enforced Gsdmc expression in parental and Brca-KO murine cancer cells, including PanO2 pancreatic cancer, MC38 colorectal cancer, Hepa-1-6 liver cancer, and B16 melanoma cells." (PMID 37883181, 2024). "In contrast, GSDMC is not expressed in the normal epidermis, but is expressed in melanoma specimens; this expression is correlated with the invasiveness and metastatic potential of melanoma cells." (PMID 27835699, 2016).
colorectal cancer (20 papers, 2016 to 2026). A primary or metastatic malignant neoplasm that affects the colon or rectum. "Gasdermin C (GSDMC) is overexpressed in human colorectal cancer (CRC); however, the molecular mechanisms underlying GSDMC regulation of CRC tumorigenesis are largely elusive." (PMID 40213993, 2025). "Compared to adjacent non‐tumor tissues, the expression of GSDMC was significantly higher in colorectal cancers." (PMID 40213993, 2025). "To investigate the functional involvement of GSDMC in intestinal tumorigenesis, we utilized the AOM-DSS model of colitis-associated colorectal cancer in Gsdmc1-4+/+ and Gsdmc1-4−/− mice." (PMID 39489845, 2024). "In the specific case of colorectal cancer, we cannot exclude the possibility that GSDMC only exerts a tumor-promoting effect in advanced stages." (PMID 39489845, 2024). "Other functions of GSDMC have been proposed, including evidence that gene manipulation of GSDMC limited or exacerbated cell proliferation in colorectal cancer cell lines upon siRNA or overexpression, respectively." (PMID 37266429, 2023). "Studies have demonstrated that GSDMC is highly expressed in metastatic melanoma and that the knockdown of GSDMC inhibits the proliferation of colorectal cancer cells, while the expression of GSDMC is suppressed in esophageal and gastric cancers." (PMID 35784306, 2022). "GSDMC gene knockout decreases colorectal cancer (CRC) cell growth, supporting the tumor-promoting effects of GSDMC." (PMID 36552744, 2022). "GSDMC (gasdermin C), a member of GSDM superfamily was found to promote cell proliferation in colorectal cancer, and high expression of GSDMC in BC and lung adenocarcinoma correlates with poor survival." (PMID 35167614, 2022). "Downregulation of GSDMC expression attenuates the proliferation of colorectal cancer cells, whereas overexpression of GSDMC contributes to its proliferation and tumorigenesis, implying that GSDMC has great potential as a therapeutic target for CRC." (PMID 35896522, 2022). "GSDMC stimulated colorectal cancer cell proliferation by interacting with transforming growth factor β receptor type II." (PMID 35535333, 2022). "In colorectal cancer cells, the high expression of GSDMC can promote cell proliferation and tumor formation by inhibiting the activity of TGFBR2." (PMID 34778452, 2021). "On the one hand, GSDMC was generally considered an oncogene that was highly expressed in cancer cells such as colorectal cancer, metastatic melanoma, and esophageal cancer." (PMID 34778452, 2021). "This study investigated the correlation between the expression of PLAU or GSDMC and the tumor microenvironment of colorectal cancer and revealed that high expression of PLAU and GSDMC maybe regulate the function of CTL cells." (PMID 41584044, 2026). "Therefore, we were unable to analyze the relationship between PLAU and GSDMC expression and the prognosis of colorectal cancer patients treated with ICIs." (PMID 41584044, 2026). "Finally, in the initial stage of this study, the correlations between PLAU and GSDMC expression and the tumor microenvironment of patients with colorectal cancer were analyzed using bioinformatics methods." (PMID 41584044, 2026). "Given the increased expression and activation of GSDMC in colorectal cancer, we next asked whether GSDMCs played a vital role in CRC development." (PMID 40213993, 2025). "Furthermore, GSDMC has been discovered to have a crucial function in colorectal cancer, lung cancer, and other solid tumors." (PMID 35677632, 2022). "Moreover, it was reported that GSDMC inhibited the TGFβR2 activation, thereby acted as an oncogene and promoted the proliferation of colorectal cancer cells." (PMID 34731088, 2021). "Furthermore, GSDMC was proved to act as an oncogene in colorectal cancer based on the observation that silence of GSDMC remarkably decreased the proliferation of colorectal cancer cells." (PMID 34731088, 2021).
colorectal cancer (continued). "In the future, we will continue to collect relevant samples of patients with colorectal cancer treated with immunotherapy and further study the correlation between PLAU and GSDMC expression and the prognosis of colorectal cancer patients treated with ICIs." (PMID 41584044, 2026). "To explore the mechanism of GSDMC in promoting CRC development, we first established CT26 and MC38 mouse colorectal cancer cell lines stably overexpressing GSDMC2–4 or expressing shRNA targeting GSDMC2‐4 (shGSDMC) and confirmed the overexpression or knockdown of GSDMC2‐4 by qPCR and Western blot." (PMID 40213993, 2025). "Moreover, studies have shown that the expression levels of GSDMC and GSDME proteins were significantly upregulated in colorectal cancer tissues." (PMID 36003332, 2022). "However, data on immunotherapy for colorectal cancer in existing databases are lacking, and the correlation between PLAU and GSDMC expression and the prognosis of patients with colorectal cancer treated with immunotherapy is currently unclear." (PMID 41584044, 2026).
lung adenocarcinoma (18 papers, 2020 to 2024). A carcinoma that arises from the lung and is characterized by the presence of malignant glandular epithelial cells. "A similar tumor-promoting role in lung adenocarcinoma was demonstrated by Wei’s Lab, upregulation of GSDMC was linked to poor outcomes, making it be a promising target for the disease." (PMID 37359371, 2023). "Overexpression of GSDMC causes poor prognosis in lung adenocarcinoma." (PMID 36199146, 2022). "Research effort is currently dedicated to explore the relationship between pyroptosis-related genes and lung cancer, which concluded that overexpression of GSDMC has a predictive ability in the prognosis of lung adenocarcinoma." (PMID 37194062, 2023). "GSDMC has also been proved to be over-expressed in lung adenocarcinoma and function as a predictive factor for poor prognosis, which inspired us to put much more effort into exploring the function of GSDMC as a prognostic biomarker in BRCA." (PMID 35957895, 2022). "Some studies suggest that GSDMC expression level is correlated with some tumors, such as lung adenocarcinoma, metastatic melanoma, esophageal cancer, and gastric cancer." (PMID 36042287, 2022). "GSDMC expression was found to be obviously upregulated in lung adenocarcinoma (LUAD) tissues by using several bioinformatics platforms and PCR detection." (PMID 34830775, 2021). "The tumor oncogene, GSDMC, can significantly promote cell proliferation and tumorigenesis in colorectal carcinogenesis and lung adenocarcinoma." (PMID 34721986, 2021). "GSDMC functioned as an oncogene, enhancing cell proliferation and tumorigenesis in lung adenocarcinoma and colorectal carcinogenesis." (PMID 33133157, 2020). "Overexpression of GSDMC also has relativity with a bad outcomes of lung adenocarcinoma patients." (PMID 37359371, 2023). "However, it has also been proved that down-regulation of GSDMD promotes gastric cancer proliferation by regulating cell cycle-related proteins and over-expression of GSDMC is a prognostic factor for predicting a poor outcome in lung adenocarcinoma." (PMID 36138348, 2022). "Studies have shown that GSDMC may act as an oncogene to promote the occurrence of colorectal and lung adenocarcinoma, while GSDME acts as a tumor suppressor in breast and liver cancer." (PMID 35008400, 2022).
metastatic melanoma (13 papers, 2012 to 2024). A melanoma that has spread from its primary site to another anatomic site. "The aberrant over-expression of GSDMC was initially identified in metastatic melanoma cells in mice, suggesting that GSDMC could promote tumor progression." (PMID 36823153, 2023). "Early studies found GSDMC was highly expressed in metastatic melanoma cells." (PMID 35547808, 2022).
glioma (8 papers, 2017 to 2022). A benign or malignant brain and spinal cord tumor that arises from glial cells (astrocytes, oligodendrocytes, ependymal cells). "Our study shows that GSDMC, GSDMD, and PJVK have transcriptional heterogeneity and are associated with glioma prognosis." (PMID 35784306, 2022). "Considering the complex role of GSDMC in different tumors, further studies should be conducted to validate the functional mechanisms of GSDMC in glioma cell and animal models." (PMID 35547808, 2022). "In addition, we explored the proteins express by CASP4, CASP9, and GSDMC in glioma patients through the Human Protein Atlas database, and CASP4, CASP9 exhibited higher staining intensity in glioma than normal brain tissues." (PMID 35547808, 2022). "Compared with HA 1800 and HMC3 cell lines, the expression levels of CASP4, CASP9 and GSDMC showed an overall upward trend, and the IL1A level showed an overall downward trend in glioma cell lines." (PMID 35547808, 2022). "CASP1 displayed the highest mutation frequency, followed by Gasdermin C (GSDMC), while CASP3, Gasdermin B (GSDMB), Gasdermin E (GSDME), and GZAMB did not display any mutations in glioma samples." (PMID 35620284, 2022). "Finally, combined with Multivariate Cox regression analyses, four PRGs (CASP4, CASP9, GSDMC, IL1A) were identified as prognostic biomarkers for glioma patients." (PMID 35547808, 2022). "Our study showed that GSDMC is positively correlated with OS and negatively correlated with WHO classification of glioma patients, suggesting that GSDMC may act as a tumor suppressor in glioma." (PMID 35547808, 2022). "Of the 11 pyroptosis regulators, 8 revealed remarkable distinctions between glioma and normal tissues, while CASP5, CASP8, and GSDMC did not." (PMID 35620284, 2022).
pancreatic cancer (8 papers, 2022 to 2026). "GSDMC is also used in the establishment of prognostic models for pancreatic cancer at this stage, indicating that it may be associated with the poor prognosis of pancreatic cancer." (PMID 39877345, 2024). "These discoveries expand previous observations describing pyroptosis-independent effects of GSDM family members, as the role of GSDMC in inducing genes related to stemness and immune evasion in pancreatic cancer." (PMID 41545335, 2026). "Genetic intervention targeting GSDMC resulted in a significant reduction in the invasion and metastasis of pancreatic cancer cells, highlighting the critical role of GSDMC in the dissemination process of PDAC." (PMID 39297408, 2024). "Our studies, using human and mouse models of pancreatic cancer, challenged the bioinformatic prediction of GSDMC's role in PDAC cell proliferation." (PMID 39297408, 2024). "An additional risk model PRG based on more immune-related genes (CASP4, GSDMC, IL-18, NLRP1, NLRP2, PLCG1, TIRAP, and TNF) was developed, which can be used to predict pancreatic cancer prognosis with an accuracy of medium to high." (PMID 37893166, 2023). "Our findings demonstrate a cell context‐dependent role of GSDMC in promoting pancreatic cancer." (PMID 39297408, 2024). "However, our understanding of the involvement of GSDMC in cancer, particularly pancreatic cancer, remained limited." (PMID 39297408, 2024). "Finally, to evaluate the risk and prognosis in pancreatic cancer more conveniently using pyroptosis-related genes, we constructed a prognostic model consisting of seven PRGs, including CASP4, GSDMC, NLRP1, PLCG1, IL-18, CASP1 and NLRP2." (PMID 35712482, 2022). "Therefore, we speculated that GSDMC contributed to the poor prognosis of pancreatic cancer mainly by promoting tumor growth and migration." (PMID 36199146, 2022). "According to this study, PRGs risk models were defined with the combination of immune and signaling pathways genes (CASP4, GSDMC, NLRP1, PLCG1, IL-18, CASP1, and NLRP2), among which CASP4, NLRP1, PLCG1, IL-18, and CASP1 are overexpressed in pancreatic cancers." (PMID 37893166, 2023).
gastric cancer (7 papers, 2016 to 2022). A primary or metastatic malignant neoplasm involving the stomach. "The high expression of GSDMC inhibits the proliferation of gastric cancer cells." (PMID 34778452, 2021). "On the other hand, GSDMC found in gastric cancer cells may be a potential tumor suppressor, with obvious cell growth inhibitory activity." (PMID 34778452, 2021). "In gastric cancer, pyroptosis-related genes such as GSDMA, GSDMB, and GSDMC were revealed to be abnormally expressed in GC and associated with tumor progression." (PMID 35198013, 2022).
colon cancer (5 papers, 2021 to 2025). "Our data suggested that Caspase‐6 activity was required for GSDMC activation in colon cancer both in vitro and in vivo." (PMID 40213993, 2025). "We found that Caspase‐6, but not Caspase‐8, mediated OGD‐induced GSDMC activation in colon cancer cells." (PMID 40213993, 2025).
esophageal cancer (5 papers, 2016 to 2022). A primary or metastatic malignant neoplasm involving the esophagus. "However, GSDMC was downregulated in GC and esophageal cancer cells and inhibited cell growth." (PMID 35547808, 2022). "GSDMC mRNA levels varied significantly between the clinical stages of four cancers, including COAD, esophageal carcinoma, KICH, and KIRP." (PMID 36003332, 2022).
liver cancer (5 papers, 2021 to 2024). An epithelial or non-epithelial malignant neoplasm that arises from the liver. "GSDMC was significantly associated with poorer prognosis liver cancer patients in our study, indicating that it acts as a tumor-promoting gene." (PMID 35047554, 2021). "The expression of CHMP4A, SCAF11, and GSDMC was high in liver cancer tissue." (PMID 35309514, 2022). "Therefore, the effect of activating GSDMC in different environments on liver cancer is worthy of further exploration." (PMID 35047554, 2021).
lung carcinoma (5 papers, 2022 to 2024). "In addition, GSDMC overexpression might be related to lung cancer progression and poor survival." (PMID 36936274, 2022).
helminth infection (4 papers, 2022 to 2025). "The role of GSDMC in the gut remains poorly understood; however, recent studies have linked it to immune defence against helminth infections." (PMID 41370284, 2025). "Outside of bacteriology, there are studies concerning the role of GSDMC in response to helminth infection, which suggests a role for GSDMC in gut immunity." (PMID 37266429, 2023). "Type 2 cytokines, IL-4 or IL-13, triggered by worm infection, drastically up-regulated the expression of GSDMC in the gut, thereby enhancing the release of antiparasitic factors from enterocytes by GSDMC-mediated pyroptosis and facilitating the clearance of worms." (PMID 36505474, 2022).
lumbar disc herniation (4 papers, 2018 to 2023). "However, CCDC26/GSDMC rs7833174 have been associated with lumbar microdiscectomy and lumbar spinal stenosis, and a different variant GSDMC rs77681114 have been associated with lumbar disc herniation." (PMID 35140737, 2021). "Moreover, GSDMC-rs77681114 was related to reduced risk of lumbar disc herniation." (PMID 37359371, 2023). "A GWAS involving 4,748 lumbar disc herniation (LDH) cases and 282,590 controls identified 37 highly correlated genetic markers associating with development of LDH at the 8q24.21 near Gasdermin-C (GSDMC) in Icelandic population." (PMID 33273635, 2020).
breast invasive carcinoma (3 papers, 2022 to 2024). "We discovered that elevated GSDMC expression was considerably linked to a worse prognosis in breast invasive carcinoma (BRCA)." (PMID 36042287, 2022).
hepatic carcinoma (3 papers, 2021 to 2025). "Additionally, GSDMA, GSDMC and PJVK were lowly expressed in hepatic carcinoma cells, especially GSDMA." (PMID 39816682, 2025).
lumbar disc degeneration (3 papers, 2018 to 2023). "Expression of GSDMC is induced in lumbar disc degeneration, and the condition is associated with SNPs of GSDMC." (PMID 37771587, 2023). "The aim of this study is to investigate the expression levels of genome-wide association studies (GWAS)-identified variants near Gasdermin-C (GSDMC) and its association with lumbar disc degeneration (LDD) in a Chinese population." (PMID 33273635, 2020).